IGFBP4 (insulin like growth factor binding protein 4)
Diseases named in the same sentence as IGFBP4 in open-access papers (continued):
Sharing a sentence is not in itself a finding about the gene and the disease.
colorectal cancer (5 papers, 2008 to 2023). A primary or metastatic malignant neoplasm that affects the colon or rectum. "By contrast, IGFBP1 and IGFBP4 protein showed medium or low expression in several tumors such as pancreatic cancer and colorectal cancer." (PMID 37088808, 2023). "In IGF-insensitive colorectal cancer cells, recombinant human IGFBP-4 was able to efficiently block colony formation, and in P19CL6 or in embryonic stem cells, knockdown of IGFBP-4 was shown to alter cardiomyogenesis and cardiac regeneration." (PMID 30061864, 2018).
gastric cancer (5 papers, 2015 to 2025). A primary or metastatic malignant neoplasm involving the stomach. "Moreover, differential gene expression analyses also found that high PAPP-A expression was associated with an increase in IGF-1 and IGFBP-4 in gastric cancer." (PMID 41303367, 2025). "While studies highlight PAPP-A as a potential biomarker in the literature, our results revealed significant differences in IGFBP-4 levels in gastric cancer patients." (PMID 41303367, 2025). "In line with previous findings, in our study, IGFBP-4 levels were also increased in gastric cancer serum samples." (PMID 41303367, 2025). "ROC analyses revealed that IGF-1, IGFBP-4, and IGFBP-5 have good discriminatory properties in the diagnosis of gastric cancer, while PAPP-A offers low diagnostic value." (PMID 41303367, 2025). "Recent studies have shown that expression levels of IGFBP-4 are significantly higher in gastric cancer tissues." (PMID 41303367, 2025). "In a study conducted with 375 cancer samples, it was also found that IGFBP-4 levels were higher in gastric cancer tissues and MKN28, MKN45, HGC27, BGC823, MGC803 and AGS gastric cell lines." (PMID 41303367, 2025). "The serum levels of total IGFBP-4 protein were significantly higher in gastric cancer patients (97.42 ng/mL) than in healthy individuals (67.88 ng/mL)." (PMID 41303367, 2025). "The findings showed that IGF-1 levels were significantly decreased in the gastric cancer group, while IGFBP-4 levels were significantly increased." (PMID 41303367, 2025). "The results of our study suggest that IGFBP-4 may have a potential role in gastric cancer diagnosis." (PMID 41303367, 2025). "In conclusion, among the IGF family members examined, IGFBP-4 may be a more potent and innovative biomarker candidate for gastric cancer." (PMID 41303367, 2025). "Similarly, a bioinformatic study demonstrated increased IGFBP-4 levels in gastric cancer tissues." (PMID 41303367, 2025). "Moreover, ROC analysis has shown that IGFBP-4 could serve as a moderate biomarker of gastric cancer diagnosis with an AUC of 0.725." (PMID 41303367, 2025). "This study investigated the biomarker potential of IGF-1, IGFBP-4, IGFBP-5, and PAPP-A in gastric cancer." (PMID 41303367, 2025). "In this study, IGF-1, IGFBP-4, IGFBP-5, and PAPP-A levels were examined in serum samples obtained from gastric cancer patients and healthy individuals." (PMID 41303367, 2025). "While IGFBP-4 showed a moderately discriminatory effect, PAPP-A had low potential for being a biomarker in gastric cancer detection." (PMID 41303367, 2025). "In this study, serum levels of IGF signaling pathway-related proteins known as IGF-1, IGFBP-4, IGFBP-5, and PAPP-A were compared between gastric cancer patients and healthy controls." (PMID 41303367, 2025). "That is, IGFBP3, IGFBP4, and IGFBP7 expression levels were higher in gastric cancer patients vs. normal in the Oncomine data." (PMID 34745945, 2021). "Expression levels of IGFBP3, IGFBP4, and IGFBP7 were significantly elevated in gastric cancer tissues, whereas those of IGFBP1 were reduced in normal tissues." (PMID 34745945, 2021). "In conclusion, this study suggests that IGF pathway components, particularly IGF-1, IGFBP-4, and IGFBP-5, might be promising biomarker candidates for gastric cancer." (PMID 41303367, 2025). "Overall, these results demonstrate that the IGF signaling pathway plays a critical role in the pathogenesis of gastric cancer and that IGF-1, IGFBP-4, and IGFBP-5, in particular, may serve as potential biomarkers for clinical applications." (PMID 41303367, 2025). "A study of 11 gastric cancer cell lines demonstrated that IGFBP1 expression levels were extremely low in all cell lines, whereas IGFBP2 and IGFBP4 were expressed in 10 and 9 cell lines, respectively, and IGFBP3, IGFBP5, and IGFBP6 were expressed in half of all cell lines." (PMID 34745945, 2021).
gastric cancer (continued). "Nevertheless, although our findings suggest a possible role for IGFBP-4 in the pathophysiology of gastric cancer, the lack of separate measurement of intact IGFBP-4 levels limits the ability to directly assess the relationship between PAPP-A-mediated proteolysis and IGF bioavailability." (PMID 41303367, 2025). "Moreover, ROC analysis showed that IGF-1, IGFBP-4, and IGFBP-5 could effectively distinguish gastric cancer from healthy controls with high sensitivity and specificity." (PMID 41303367, 2025). "However, there is no clinical study on serum IGFBP-4 levels in patients with gastric cancer." (PMID 41303367, 2025). "We performed Quantitative Real-time PCR (qPCR) on 6 up-regulated genes (COL1A, BGN, SPP1, MELK, IGFBP4, SPARC) and 4 down-regulated genes (PGC, SST, MT1X, S100P) to verify our data in gastric cancer tissues (Tumor) and noncancerous tissues (Normal)." (PMID 25928635, 2015).
Obesity (5 papers, 2021 to 2025). Accumulation of substantial excess body fat. "In a previous study, we reported a significant rise in IGFBP4 levels under conditions of hypoxia in a cohort diagnosed with obesity and OSA." (PMID 40806552, 2025). "IGFBP-4 is known to have roles in skeletal growth and bone physiology, and in children with obesity, it positively correlates with fasting insulin concentrations." (PMID 38712328, 2024). "Mean concentrations of IGFBP3 and IGFBP4 in the obesity group (OB) were higher than in the control group (HC)." (PMID 34371941, 2021). "The BMI-stratified analysis revealed significant differences in ESS, OSA indices (AI, HI, AHI), HbA1c, C-peptide, insulin, IGFBP4, and leptin levels in the obese group, consistent with obesity being an independent contributor to OSA severity and metabolic dysregulation." (PMID 41458545, 2025). "We observed a significant induction in the levels of C3, CP enzyme, growth factor IGFBP4, and cytokine CXCL10 and interferon signaling-related genes including (IFNβ, ISG15, MX2 and OASL2), some of which have been recognized for their role either in obesity or inflammation." (PMID 33672392, 2021).
adenoma (4 papers, 2004 to 2022). A neoplasm arising from the epithelium. "At difference, a significant reduction of IGFBP4 levels was highlighted in cancers with respect to both adenomas and hyperplastic nodules." (PMID 34350538, 2022). "On the other hand, in subjects with primary hyperparathyroidism due to adenoma or hyperplasia, IGFBP-4 levels were found to be subnormal." (PMID 21274331, 2010). "Our analysis demonstrated significantly lower expression of IGFBP-4, -5, and -7 in the malignant adenocarcinomas than in the benign adenomas or borderline tumours." (PMID 15471544, 2004). "We evaluated mRNA expression of IGFBP4, IGF1 and IGF1R in thyroid cancers, adenomas and hyperplastic nodules in comparison with their benign counterparts without observing any statistically significant differences." (PMID 34350538, 2022). "The analysis of the IGF1 cascade in the “surgical series” did not showed any difference in IGFBP4, IGF1 and IGF1R mRNA expression in cancer, adenomas and hyperplastic nodules compared to the respective benign counterparts." (PMID 34350538, 2022).
COVID-19 (4 papers, 2021 to 2026). A disease caused by infection with severe acute respiratory syndrome coronavirus 2. "Except IGFBP4, the other IGFBPs are common to severe COVID-19." (PMID 37301958, 2023). "Finally, a total of eleven differential factors related to COVID-19 disease severity were identified, including: TRAIL R1, IGFBP-1, IGFBP-4, VCAM-1, sFRP-3, FABP2, Transferrin, GDF15, IL-1F7 (also known as IL-37), IL-5Rα, and CD200." (PMID 34335566, 2021).
fibrosis (4 papers, 2019 to 2026). the formation of excess fibrous connective tissue in an organ or tissue in a reparative or reactive process. "IGFBP-4 blocks TGF-β-induced ECM production and inhibits ECM production in lung and skin cells in vitro, while IGFBP-4 knockout reduces bleomycin-induced fibrosis." (PMID 41226289, 2025). "At 4 weeks post‐MI, Masson's trichrome staining showed no significant improvements in infarct size in VEGF‐treated mice compared with PBS‐treated mice, but distinct reductions in IGFBP‐4–treated and dual VEGF/IGFBP‐4–treated mice, indicative of decreased degree of cardiac fibrosis." (PMID 32597006, 2020).
liver cancer (4 papers, 2012 to 2025). An epithelial or non-epithelial malignant neoplasm that arises from the liver. "The results revealed that expression of SMYD3 was upregulated, while IGFBP4 was downregulated in liver cancer tissues compared to noncancerous liver tissues." (PMID 36575438, 2022).
Nephropathy (4 papers, 2016 to 2023). A nonspecific term referring to disease or damage of the kidneys. "Among other kidney diseases, IGFBP-4 was found high expressed in the serum of CKD patients, and this is correlated with the kidney failure degree, the reduced osteogenesis during osteodystrophia, and growth retardation in children with CKD." (PMID 35002740, 2021). "In this regard, serum IGFBP-4 performs better than eGFR in predicting chronicity of renal disease." (PMID 27019456, 2016). "We next asked if the differences seen in serum IGFBP-4 levels in different subjects with renal disease might be affected by differences in the degree of proteinuria." (PMID 27019456, 2016). "Cardiovascular events are endpoint of death in the vast majority of patients with DN, in this way, IGFBP-4 is potential to serve as a predictive marker for DN patients without affected by their own kidney disease." (PMID 35002740, 2021). "Serum IGFBP-4 levels did not differentiate those with active renal disease from those with non-active renal disease (1469 ± 124 vs 1232 ± 223 ng/ml, P = 0.363)." (PMID 27019456, 2016). "Additionally, the association between the plasma levels of NGAL, IGFBP-1, IGFBP-3, and IGFBP-4 in patients with DN were compared to those in patients with T2D without kidney disease and control participants." (PMID 35148702, 2022). "People with DN have a significant increase in their plasma IGFBP-1 and IGFBP-4, more importantly, IGFBP-4 fragments (including N- and C-terminal fragments (NT-IGFBP-4 and CT-IGFBP-4)) are related to cardiovascular mortality in type 1 diabetes patients no matter with or without nephropathy." (PMID 35002740, 2021).
renal cell carcinoma (4 papers, 2013 to 2023). "So far, only IGFBP4 has been reported to activate Wnt signaling pathway in renal cell carcinoma." (PMID 23767917, 2013). "IGFBP4 activates the signaling pathway Wnt/β-catenin and induces M-CAM expression in human renal cell carcinoma." (PMID 37088808, 2023).
acute coronary syndrome (3 papers, 2018 to 2023). Signs and symptoms related to acute ischemia of the myocardium secondary to coronary artery disease. "PAPP-A-derived IGFBP-4 proteolytic fragments are considered to be diagnostic and prognostic biomarkers of various cardiovascular diseases (CVDs), such as acute coronary syndrome (ACS), acute heart failure, and ischemia." (PMID 37176126, 2023). "Previous studies have shown that PAPP-A-specific IGFBP-4 proteolysis is involved in the pathogenesis of cardiovascular diseases, such as ischemia, heart failure, and acute coronary syndrome." (PMID 37176126, 2023). "PAPP-A, IGFBP-4, and IGFBP-4 proteolytic fragments play a crucial role in the pathogenesis of CVDs, including coronary heart disease, acute coronary syndrome, and acute heart failure." (PMID 37176126, 2023). "Due to the recent discovery of Stanniocalcin-2 as a novel proteinase inhibitor of PAPP-A, we considered that it could also reflect PAPP-A enzymatic activity, with potential prognostic implications in the setting of acute coronary syndrome similarly to IGFBP-4." (PMID 29712555, 2018).
breast tumor (3 papers, 2008 to 2014). "Another member of set 2 was IGFBP4, which has been widely detected in breast tumors and cell lines, and previously correlated with ER expression." (PMID 20569502, 2010). "In an independent series of breast tumor samples (19 nonrelapsing and 14 relapsing), reduced expression of ESR1/ERα, IGFBP4, SNCG, BCL2, and FOS was observed in the relapsing group and was associated with a shorter overall survival." (PMID 18928543, 2008).
depression (3 papers, 2023 to 2025). "Additionally, substantial evidence suggests that exposures like smoking and depression are associated with IGFBP4 and CDCP151,52." (PMID 41290610, 2025). "In a rat model of depression, it was found that acute lipopolysaccharide (LPS) injections significantly increased IGFBP-4 levels in the frontal cortex but not the hippocampus." (PMID 40141202, 2025). "Finally, we have found no study addressing peripheral IGFBP-4, IGFBP-5 and IGFBP-6 levels in the context of human depression." (PMID 37894932, 2023).
fetal growth restriction (3 papers, 2014 to 2020). A fetus that does not grow beyond the 10th percentile of conventionally accepted weight for gestational age. "The inhibitory effect of IGFBP-4 on trophoblast migration may, at least in part, underlie the association between elevated circulating levels of IGFBP-4 in early pregnancy and the subsequent development of fetal growth restriction." (PMID 25475528, 2014). "Interestingly, high IGFBP-4 concentrations have previously been linked to fetal growth restriction in human gestation, and less proteolytic cleavage might be due to higher IGFBP-4 and lower IGF-1 levels." (PMID 29946296, 2018). "Maternal serum levels of IGFBP-4 in early pregnancy have been reported to be significantly altered in cases with later development of fetal growth restriction (FGR) when compared to normal pregnancies, thus confirming its function as an enhancer of placental growth and development." (PMID 33184413, 2020).
glioblastoma (3 papers, 2009 to 2025). The most malignant astrocytic tumor (WHO grade IV). "It has recently been demonstrated that IGFBP4 (another protein selected in our study) has a role in promoting glioblastoma progression in adults, and in regulating factors relating to extracellular matrix formation and tumor invasion." (PMID 28526811, 2017).
Insulin resistance (3 papers, 2018 to 2024). Increased resistance towards insulin, that is, diminished effectiveness of insulin in reducing blood glucose levels. "Here, we found genes related to insulin resistance and DM2 (PTPRF and CTLA4 altered in BSCL2mut; IGFBP4 altered in both CGL types)." (PMID 38755198, 2024). "Therefore, although the drug in group B can increase the level of IGFBP4, it does not show much difference in the improvement of glucose tolerance and insulin resistance as compared with the drug in group A." (PMID 30302116, 2018).
lupus (3 papers, 2016 to 2022). "In SLE, IGFBP2, IGFBP4 and IGFBP6 were discovered by array-based proteomic screening as diagnostic biomarkers for lupus." (PMID 30214426, 2018). "Another SLE marker, IGFBP4, was mainly increased in lupus nephritis patients, which makes it a good indicator for renal pathology chronicity changes." (PMID 30214426, 2018). "Although it has been reported that circulating IGFBP-4 levels increase slightly with age in healthy female adults, we did not detect any age-, gender- or ethnic-differences in serum IGFBP-4 concentrations among the lupus patients and controls (data not shown)." (PMID 27019456, 2016). "Serum IGFBP-4 did not correlate well with systemic lupus erythematosus disease activity index (SLEDAI), renal SLEDAI or proteinuria, but it did correlate with estimated glomerular filtration rate (R = 0.609, P < 0.0001)." (PMID 27019456, 2016).
lupus nephritis (3 papers, 2016 to 2022). Glomerulonephritis in the context of systemic lupus erythematosus. "Other studies have found that the serum concentration of IGFBP-4 is closely associated with the chronic index of lupus nephritis and the estimated glomerular filtration rate (eGFR), and can be used as a marker for lupus nephritis." (PMID 35002740, 2021). "IGFBP-4 emerges a potential marker of lupus nephritis, reflective of renal pathology chronicity changes." (PMID 27019456, 2016). "In this study we found Insulin-like growth factor binding protein-4 (IGFBP-4) was significantly elevated in lupus nephritis, particularly those with renal pathology chronicity changes." (PMID 27019456, 2016).
myocardial ischemia (3 papers, 2018 to 2022). A disorder of cardiac function caused by insufficient blood flow to the muscle tissue of the heart. "Furthermore, we showed that Wnt inhibitors insulin-like growth factor binding protein 4 (IGFBP-4) and Dickkopf-1 (DKK1) played opposing roles in cardiac ischemia via differential targeting to LRP5/6 and β-catenin." (PMID 31881970, 2019).
renal carcinoma (3 papers, 2017 to 2022). A carcinoma arising from the epithelium of the renal parenchyma or the renal pelvis. "Overexpression of IGFBP4 in primary renal cancer cells promotes cell proliferation, invasion and migration." (PMID 35682969, 2022). "Transfecting primary renal cancer cell lines with IGFBP4 increased proliferation, invasion, and motility, whereas knocking down the gene in metastatic renal cancer cell lines decreased proliferation." (PMID 28443133, 2017). "The phosphorylation of Disheveled (Dvl), insulin-like growth factor binding protein 4 (IGFBP4), an opponent of the Wnt/β-catenin signaling, was discovered to trigger Wnt/β-catenin signaling pathway and to encourage the expression of CD146 in renal carcinoma cells." (PMID 31572064, 2019).
chronic kidney disease (2 papers, 2016 to 2019). Impairment of the renal function secondary to chronic kidney damage persisting for three or more months. "As for IGFBP4, in a previous study, its serum level was fourfold higher in children with chronic renal failure, and this increase was related to the degree of renal dysfunction." (PMID 31772941, 2019). "As serum IGFBP-4 correlated with eGFR in patients with LN, and since it has been reported that IGFBP-4 is increased in patients with chronic renal failure, we next explored if elevated serum IGFBP-4 is indicative of chronic lupus nephritis." (PMID 27019456, 2016).
endometrial cancer (2 papers, 2023 to 2025). Primary or metastatic malignant neoplasm involving the endometrium (mucous membrane that lines the endometrial cavity). "Additionally, several researchers have determined that in endometrial cancer, the YTHDF1 enhances the growth of tumors by controlling the ERK/NF‐κB/AKT signaling cascade via the PAPPA/IGFBP4 axis." (PMID 39821576, 2025).
endometriosis (2 papers, 2021 to 2025). The growth of functional endometrial tissue in anatomic sites outside the uterine body. "Our results showing IGF1 increasing and IGFBP1 and IGFBP4 reducing the odds for an endometriosis diagnosis suggest an opposing function of IGF1 and their binding proteins in bloods collected years prior to endometriosis diagnosis." (PMID 40215752, 2025).